JAK2 (Janus kinase 2)
Diseases named in the same sentence as JAK2 in open-access papers (continued):
Sharing a sentence is not in itself a finding about the gene and the disease.
myeloproliferative neoplasm (continued). "Fedratinib (SAR302503; TG101348) is a JAK2-selective inhibitor that was developed as a treatment for MPNs based on pre-clinical data that showed it caused a reduction in JAK2 mutant allele burden and BMF in murine models of myeloproliferative disease." (PMID 26357842, 2015). "Inhibition of JAK2 is an important clinical target, particularly for myeloproliferative disorders." (PMID 25656053, 2015). "The discovery of a mutation in the Janus kinase 2 (JAK2) gene opened a new era in the understanding of BCR-ABL- negative myeloproliferative neoplasms (MPNs)." (PMID 24475114, 2014). "A somatic mutation of JAK2, coding for constitutively activated Jak2-V617F, is frequently observed in BCR/ABL1-negative myeloproliferative neoplasms (MPNs): 96% in polycythemia vera (PV), 55% in essential thrombocythemia (ET), and 65% in primary myelofibrosis (PMF)." (PMID 24404189, 2014). "JAK2 inhibitors are potential drugs for the treatment of myeloproliferative neoplasms." (PMID 23739681, 2013). "Aberrant JAK2 signalling plays a central role in myeloproliferative neoplasms (MPN)." (PMID 24237791, 2013). "The Janus kinase 2 mutant V617F occurs with high frequency in myeloproliferative neoplasms." (PMID 23301855, 2013). "Non-reactive platelet counts elevation occurs mainly in myeloproliferative disorders (MPDs), which have been reported to be closely associated with JAK2 V617F mutation." (PMID 23469088, 2013). "Hyperactivation of JAK2 occurs in myeloproliferative neoplasms by different mechanisms." (PMID 22400031, 2012). "JAK2 V617F-positive myeloproliferative neoplasm was diagnosed." (PMID 22480324, 2012). "The non-receptor tyrosine kinase JAK2 is implicated in a group of myeloproliferative neoplasms including polycythemia vera, essential thrombocythemia, and primary myelofibrosis." (PMID 22916261, 2012). "Here mutations in the gp130-bound and activated JAK2-gene – which lead to a permanent activation of the STAT pathway and carry the potential of a subsequent malignant cell transformation – are causally related to myeloproliferative neoplasms." (PMID 22745821, 2012). "However, JAK2 inhibitors are unable to target uncommitted hematopoietic progenitors responsible of the initiation of the myeloproliferative disease." (PMID 22400031, 2012). "Indeed, recent studies have reported on the roles of bone marrow-derived stromal cells in protecting myeloproliferative neoplasms or acute myeloid leukaemia from the effects of JAK2 or FLT3 tyrosine kinase inhibitors, respectively." (PMID 21897388, 2011). "To test this hypothesis, we retrospectively analyzed a cohort of 270 JAK2 V617F-positive patients from the Johns Hopkins Center for the Chronic Myeloproliferative Disorders." (PMID 22084670, 2011). "Polycythemia vera (PV) and essential thrombocythemia (ET) are two Philadelphia-negative myeloproliferative neoplasms (MPN) associated with an acquired mutation in the JAK2 tyrosine kinase gene." (PMID 21623459, 2011). "The JAK2 V617F mutation, first described in 2005, has become an important diagnostic criterion in Philadelphia chromosome negative myeloproliferative diseases, especially in polycythemia vera (PV)." (PMID 22028900, 2011). "Finally, the BM histology may reveal a myeloproliferative neoplasm or an MDS/MPN overlap disease, which can be accompanied by the JAK2 mutation V617F." (PMID 21317447, 2010). "The critical role of JAK2 in signal transduction by hematopoietic growth factor and cytokine receptors suggested that JAK2 might have abnormal tyrosine kinase activity in chronic myeloproliferative disease." (PMID 17032464, 2006). "In addition to MLN-eo-TK, JAK2 rearrangements can also be found in BCR::ABL1-negative myeloproliferative neoplasms (MPN), myelodysplastic neoplasms (MDS), MDS/MPN overlap syndromes, B/T lymphomas, acute myeloid (AML), lymphoblastic (ALL) or mixed- phenotype acute leukemia (MPAL)." (PMID 41530508, 2026).
myeloproliferative neoplasm (continued). "However, the lack of association between JAK2 mutations and cytopenia development merits consideration of alternative phenotypic changes preceding myeloproliferative neoplasms (MPNs)." (PMID 40524801, 2025). "Thus, in addition to JAK2 V617F, TYK2 V678F mutations may also contribute to the development of myeloproliferative disorders, including MDS." (PMID 40519492, 2025). "The majority of patients presenting with SVT at diagnosis were classified as myeloproliferative neoplasm with heterozygous JAK2 mutation (87% of cases vs. 69% in PV/ET control group, p < 0.05), characterized by low JAK2 allele burden and no high-risk mutations." (PMID 38263537, 2024). "Despite discovery of the JAK2, CALR and MPL driver mutations, the molecular etiology of Myeloproliferative Neoplasms (MPN) remains incompletely understood." (PMID 36709354, 2023). "The JAK2 exon 14 mutation identified in this case is not an established driver mutation for myeloproliferative neoplasm, and its clinical implication remains unknown." (PMID 35237453, 2022). "A marked reduction in PP2A activity was also found in CD34+ stem cells isolated from bone marrow and peripheral blood of JAK2-driven myeloproliferative neoplasms (MPN), compared with those isolated from healthy individuals." (PMID 36345878, 2022). "LNK-dependent negative control of JAK2 is crucial, as evidenced by the more rapid development of myeloproliferative neoplasm in LNK−/− mice expressing mutated JAK2V617F, and the description of myeloproliferative neoplasms associated with LNK mutations in humans." (PMID 36077192, 2022). "Janus kinase 2 (JAK2) kinase inhibitors drive the development of myeloproliferative neoplasms (MPN)." (PMID 35806290, 2022). "Several cases such as myeloproliferative neoplasms (MPN) with the coexistence of JAK2 and BCR-ABL have been reported." (PMID 36518237, 2022). "The myeloproliferative neoplasms, polycythemia vera, essential thrombocytosis and primary myelofibrosis share driver mutations that either activate the thrombopoietin receptor, MPL, or indirectly activate it through mutations in the gene for JAK2, its cognate tyrosine kinase." (PMID 33777803, 2021). "Notably, high PD-L1 expression in monocytes has also been reported in non-Philadelphia chromosome myeloproliferative neoplasms with a JAK2 V617F mutation via STAT3/STAT5-dependent transcriptional induction." (PMID 34508131, 2021). "For instance, a combination of PIM inhibitors with JAK2 inhibitor in myeloproliferative neoplasms (MPN) and a combination with cytarabine in AML overcame drug resistance." (PMID 34503111, 2021). "A finding which might imply a significant role of JAK2 mutation in the development of PVT in patients with chronic liver disease even without overt myeloproliferative neoplasms (MPNs)." (PMID 33507708, 2021). "JAK2 is the most intensively investigated member of the JAK family as it is has been shown to play a major role in tumour growth and progression, plus the pathogenic JAK2V617F mutation is present in the majority of patients with myeloproliferative neoplasms (MPNs)." (PMID 32987782, 2020). "JAK2 (V617F) allelic burden is the main genetic driver behind and a potential differentiator between individual myeloproliferative neoplasm (MPN) subtypes." (PMID 32986384, 2020). "In particular, MULAN was able to detect a mutability increase event during the evolution of JAK2-Negative Myeloproliferative Neoplasm, that could be linked to the mutation in the gene with known associations with genetic instability." (PMID 33253159, 2020). "While JAK2-mutations are among the most common genetic aberrations detected in aging-associated clonal hematopoiesis they do not necessarily lead to development of myeloproliferative neoplasms or hematologic cancers." (PMID 31398915, 2019).
myeloproliferative neoplasm (continued). "Potential contributing etiologies of breakthrough VTE include subtherapeutic anticoagulation (often attributed to suboptimal adherence), antiphospholipid syndrome, established myeloproliferative neoplasm, JAK2 V617F mutation in the absence of an established myeloproliferative neoplasm, and cancer." (PMID 29760849, 2018). "Despite its general role as a tumor suppressor, a recent study identified a strong synthetic lethal relationship between RECQL5 and an activating V617F mutation in the JAK2 non-receptor tyrosine kinase, a common oncogenic lesion in patients with myeloproliferative neoplasms (MPN)." (PMID 28100692, 2017). "The presence of acquired mutations within the JAK2, CALR, and MPL genes in the majority of patients with myeloproliferative neoplasms (MPN) affords the opportunity to utilise these mutations as markers of minimal residual disease (MRD)." (PMID 27840830, 2016). "Somatic frameshift mutations in exon 9 of calreticulin (CALR) have been identified in a large proportion of JAK2- or MPL-negative myeloproliferative neoplasm (MPN) patients, including those with primary myelofibrosis (PMF) and essential thrombocythemia (ET)." (PMID 26377485, 2016). "Somatic calreticulin (CALR), Janus kinase 2 (JAK2), and thrombopoietin receptor (MPL) mutations essentially show mutual exclusion in myeloproliferative neoplasms (MPN), suggesting that they activate common oncogenic pathways." (PMID 27177927, 2016). "This is exemplified by the recent discovery that patients with myeloproliferative neoplasms (MPNs) that did not have a janus kinase 2 (JAK2) mutation (a mutation occurring in the vast majority of patients) are characterized by somatic mutations in their calreticulin gene." (PMID 25688334, 2015). "However, mutations which are reported to play a major role in myeloproliferative neoplasms, such as ten-eleven translocation-2 (TET2), runt-related transcription factor 1 isoform (RUNX1), janus kinase 2 (JAK2) V617F, and Soc-2 suppressor of clear homolog SHOC2 are not involved in JMML." (PMID 22162691, 2012). "Thus, further preclinical evaluation of combinations of JAK2 inhibitors with Bcl-2 family antagonists that also tackle Mcl-1, besides Bcl-xL, is warranted to assess the therapeutic potential for the treatment of chronic myeloproliferative neoplasms." (PMID 21247487, 2011). "Their findings using a murine myeloproliferative neoplasm (MPN) model indicate that treatment with a selective JAK2 inhibitor attenuates the MPN phenotype by diminishing the myeloid progenitor population." (PMID 21533169, 2011). "Panobinostat, a pan-HDAC inhibitor, and TG101209, a JAK2 inhibitor, have been studied in targeting JAK2V617F-positive myeloproliferative neoplasms (MPNs)." (PMID 40374809, 2025). "The continuous activation of the JAK2/STAT3 pathway fosters the advancement of a variety of diseases, encompassing myeloproliferative disorders, solid tumors, interstitial lung conditions, and osteoarthritis." (PMID 38794201, 2024). "Given the thrombocytosis and leucocytosis, additional tests, including JAK2 and BCR-ABL, were performed as suspicion of a myeloproliferative disease was high." (PMID 39371771, 2024). "In a myeloproliferative neoplasms model, CUR activates the JAK2/STAT pathway, inducing apoptosis and inhibiting proliferation, thus exerting an antitumor effect on human JAK2-mutated cells." (PMID 37497225, 2023). "The most prevalent transgenic mouse line in existing publications is the Myeloproliferative neoplasm model (MGI:6356966), featuring the Jak2 (Janus kinase 2) gene." (PMID 38179140, 2023). "How and if JAK2/STAT and Wnt/β-catenin cooperate during megakaryopoiesis as well as in the context of myeloproliferative neoplasms requires additional investigations." (PMID 38067194, 2023). "For example, the order in which the two driver events in JAK2 and TET2 are acquired in myeloproliferative neoplasms affects the clinical course of the disease." (PMID 36428782, 2022).
myeloproliferative neoplasm (continued). "The Janus kinase 2 (JAK2V617F) mutation is the main molecular marker of the Philadelphia-negative chronic myeloproliferative neoplasms (MPN), responsible for 95% of polycythaemia; 50% of thrombocythemia vera; and myelofibrosis cases." (PMID 35800822, 2022). "Here, the authors show that HOXA9 has a binary switch function that can clinically stratify AML patients, and model how the interactions with JAK2, TET2 and NOTCH impact myeloproliferative neoplasms." (PMID 36192425, 2022). "Additionally, it is important to note that these findings are not essentially new since previous reports from a decade ago and earlier had indicated an association between JAK-2 mutation and cerebral venous thrombosis, also without laboratory evidence for the myeloproliferative disorder." (PMID 35493844, 2022). "Ruxolitinib is widely indicated for the treatment of the myeloproliferative neoplasms (MPNs) via inhibition of dysregulated janus kinases (JAK1 and JAK2) despite the side effects such as thrombocytopenia, anemia, and neutropenia." (PMID 34445192, 2021). "Ruxolitinib is the first janus kinase 1 (JAK1) and JAK2 inhibitor that was approved by the United States Food and Drug Administration (FDA) agency for the treatment of myeloproliferative neoplasms." (PMID 33589712, 2021). "As a major STAT5 target gene, its expression is strongly increased in a range of myeloproliferative disorders where STAT5 is activated, including BCR/ABL-induced CML and JAK2 V617F-induced disease." (PMID 34604264, 2021). "Ruxolitinib is a novel biologic agent used for the treatment of myeloproliferative diseases, that inhibits Janus kinase 1 (JAK1) and Janus kinase 2 (JAK2)." (PMID 33413168, 2021). "Another gene located at 9p24 is Janus kinase 2 (JAK2), which has gained much attention in the context of myeloproliferative diseases." (PMID 33567641, 2021). "The aim of this review is to discuss the emerging role of DDR alterations in the pathophysiology of two chronic myeloproliferative disease states, BCR-ABL-positive CML and JAK2 V617F-positive PV." (PMID 32272770, 2020). "Finally, although the presence of the V617F mutation in the Janus kinase 2 gene (JAK2V617F) has been identified in 6.6% of CVT patients, only 3.8% had a diagnosis of myeloproliferative neoplasm (MPN) throughout their lives." (PMID 32164214, 2020). "Very recently, the JAK2 V617F mutation was detected in two B-cell chronic lymphocytic leukemia patients without coexisting Philadelphia chromosome-negative myeloproliferative neoplasms, thus suggesting that, although rare, this JAK2-activating mutation may occur also in B-CLL." (PMID 26413812, 2015). "Ruxolitinib is an orally available and potent selective inhibitor of JAK1 and JAK2, and it is the most advanced JAK1/JAK2 inhibitor in development for the treatment of myeloproliferative neoplasms." (PMID 26316489, 2015). "The recent discovery of CALR mutations in essential thrombocythemia (ET) and primary myelofibrosis (PMF) patients without JAK2/MPL mutations has emerged as a relevant finding for the molecular diagnosis of these myeloproliferative neoplasms (MPN)." (PMID 25068507, 2014). "In 2005, a somatic activating point mutation in Janus kinase 2 (Jak2)—Jak2V617F was discovered in Philadelphia chromosome-negative myeloproliferative neoplasm (MPN) patients." (PMID 23301855, 2013). "Mutation(s) of the JAK2 gene (V617F) has been described in a significant proportion of Philadelphia negative Myeloproliferative Neoplasms (MPN) patients and its detection is now a cornerstone in the diagnostic algorithm." (PMID 23865766, 2013). "Key inclusion criteria were a negative test for JAK2 V617F between 1 January 2014 and 31 December 2018; no diagnosis of myeloproliferative neoplasm; no prior investigation for myeloproliferative neoplasm; Hb or Hct above the WHO thresholds for polycythaemia." (PMID 40589100, 2025).
myeloproliferative neoplasm (continued). "The JAK2 46/1 (“GGCC”) haplotype is an inherited genetic variation within the Jak2 gene locus that has become a focal point in research related to oncogenesis, particularly in myeloproliferative neoplasms (MPNs)." (PMID 41226376, 2025). "JAK2, a non-receptor tyrosine kinase, is commonly mutant in hematologic malignancies such as myeloproliferative neoplasm." (PMID 39844043, 2025). "Interestingly, the phenotypic shift toward a BCR-like phenotype in response to ruxolitinib treatment was reported in a 41-year-old male with a myeloproliferative neoplasm and BCR::JAK2 gene fusion." (PMID 41009670, 2025). "Background and Objectives: Philadelphia (Ph)-negative myeloproliferative neoplasms can exhibit defects in Janus kinase 2 (JAK2), Calreticulin (CalR), and MPL genes." (PMID 40572650, 2025). "In addition to JAK2 (Janus kinase 2), MPL plays a significant role in the pathogenesis of myeloproliferative neoplasms (MPN), particularly in essential thrombocythemia (ET) and myelofibrosis (MF)." (PMID 40066097, 2025). "Subsequent cytogenetic analysis of myeloproliferative disorders did not detect any additional genetic alterations, including mutations in CALR, MPL, BCR-ABL1, or other JAK2 mutations, aside from JAK2 V617F." (PMID 41179685, 2025). "Mutations in JAK2, CALR, and MPL are major disease drivers for myeloproliferative neoplasm (MPNs), and can initiate or promote MPNs with or without other co-mutations." (PMID 39682303, 2024). "In another study, it was reported that mouse models of CH carrying mutations in Tet2, Dnmt3a, Asxl1, and Jak2 demonstrated that obesity accelerated the size of CH clones and increased the risk of developing a myeloproliferative neoplasm (MPN)-like phenotype, regardless of the specific mutation." (PMID 39119355, 2024). "A year after the identification of the JAK2 mutation as a pivotal factor in the pathogenesis of myeloproliferative neoplasms (MPN), researchers began to investigate patients lacking JAK2 alterations." (PMID 39682300, 2024). "Interestingly, another recent study (n = 7) discovered that HSP90 inhibition disrupted JAK-STAT signalling by potently decreasing JAK2 expression and the phosphorylation of STAT3 and STAT5 in patients with myeloproliferative neoplasms." (PMID 38274815, 2023). "There is substantial doubt about the prognosis in JAK2 V617F positive individuals without evident signs of myeloproliferative disease." (PMID 37370982, 2023). "In contrast, the presence of JAK2, CALR, or MPL mutations in the absence of SF3B1 should orient the diagnosis to a myeloproliferative disorder." (PMID 37370785, 2023). "JAK2 V617F mutation could also interferes with epigenetic processes and recently the role of phosphorylate arginine methyltransferase PRMT5 in myeloproliferative neoplasm (MPN) pathogenesis was investigated." (PMID 35562964, 2022). "Both patients, aged 72 and 73 years, with JAK2-negative suspected PV, had typical features of myeloproliferative disorders, including splenomegaly, and required repeated phlebotomy and hydroxyurea therapy." (PMID 36290845, 2022). "Multiple studies have tried to determine if JAK2 V617F allelic burden influences the risk of thrombotic events, not just in PV but in other BCR-ABL1-negative myeloproliferative neoplasms (Ph- MPNs) as well." (PMID 34833034, 2021). "In another report, PLEK2 was found to be an effector of the JAK2/STAT5 pathway and an important regulator in the pathogenesis of JAK2V617F-induced myeloproliferative neoplasms, suggesting that PLEK2 is a feasible therapeutic target of myeloproliferative neoplasms." (PMID 34394345, 2021). "This study was conducted to evaluate the frequency of JAK2, CALR, and MPL mutations in BCR-ABL negative myeloproliferative neoplasms and their association with demographic data and hematologic parameters in a referral center, in the Middle East." (PMID 33936230, 2021).